INS (insulin)
Diseases named in the same sentence as INS in open-access papers (continued):
Sharing a sentence is not in itself a finding about the gene and the disease.
Hyperinsulinemia (continued). "We noticed that another member of the SP family, SP3, is also predicted by GLADIATOR to participate in the hyperinsulinism module, and found that a recent study suggests a new mechanism involving both SP1 and SP3 in mediating insulin activation of glucokinase transcription." (PMID 28549478, 2017). "Insulin was demonstrated to counteract lipid-mediated CD36 ubiquitination and degradation, so we examined if the hyperinsulinemia observed in MetS mice after a lipid load, could be responsible for the absent response of CD36 to dietary lipid." (PMID 26727015, 2016). "Indeed, it was found that the H3 and H4 histones in the proximal promoter region of the insulin gene transcription factor, pancreatic duodenal homeobox-1 (PDX1), were hyperacetylated, ultimately leading to hyperinsulinemia." (PMID 26861388, 2016). "The serum levels of insulin were not routinely determined in patients with AMI; thus, we were unable to elucidate the association between glycemic gaps and hyperinsulinemia." (PMID 27291987, 2016). "CoQ10 supplementation also prevented hyperinsulinemia in recuperated rats; however, hepatic insulin signaling protein dysregulation was not normalized by CoQ10 supplementation." (PMID 26718412, 2016). "In HINS, IGT, and T2DM groups, the M values in the fasting hyperinsulinemia subgroup (fasting insulin level >15 μIU/mL) were lower than those in the nonfasting hyperinsulinemia subgroup (fasting insulin level <15 μIU/mL)." (PMID 26770991, 2016). "C‐peptide levels were found to be unchanged in the old mice during the fasted state, indicating that hyperinsulinemia is established through a reduced clearance of insulin by the liver rather than through an increased pancreatic insulin secretion." (PMID 27095270, 2016). "Taken together, these data suggest that Map4k4 is not required to mediate hyperinsulinemia in response to acute stress but is required for maintaining insulin levels in long term HFD stress." (PMID 27226575, 2016). "However, as most of the studies demonstrated insulin detemir’s brain efficacy when applied acutely, it is still unknown whether these CNS effects will prevail in the long-run or whether undesired effects due to hyperinsulinemia in the brain will become apparent." (PMID 27589235, 2016). "The hyperinsulinism seen in these patients appear to be due to a reduction in the clearance of insulin rather than the increased release of insulin, since C-peptide concentrations are within normal ranges." (PMID 27065949, 2016). "While several reports have investigated the role of hyperinsulinemia in the endothelium and in the liver and muscle, studies in which insulin is used at physiological concentrations are lacking." (PMID 26297582, 2015). "We found that relative to calcium-replete controls, rats fed low-calcium diet had improved insulin sensitivity and did not develop hyperinsulinemia when fed the high-fructose diet." (PMID 26516336, 2015). "In the current study, consumption of both saury oil and an LCMUFA concentrate improved hyperinsulinemia in obese mice; these data are consistent with our previous research, which indicated a beneficial effect of LCMUFA-rich oil on insulin sensitivity in the MetS mouse model." (PMID 26627187, 2015). "Hyperinsulinemia may also promote carcinogenesis indirectly through its effects on IGF-1, as insulin inhibits IGF-1 binding proteins and thus increases the bioavailability of IGF-1." (PMID 26690494, 2015). "Mitochondrial performance and mass were markedly reduced in the soleus muscle of STZ-induced diabetic mice, but not in high fat diet induced diabetic mice with hyperinsulinemia, indicating the significance of insulin in maintaining mitochondrial function." (PMID 26060824, 2015). "Furthermore, twofold increase in the blood insulin level (20 pg/L) in the NASH induced group was compared to the control group (10.2 pg/L), suggesting hyperinsulinemia in the NASH induced group." (PMID 26576191, 2015).
Hyperinsulinemia (continued). "Insulin is the primary hormonal mediator of energy storage, and while hyperinsulinemia is common in PCOS, it is unclear whether it is due to excessive insulin secretion, decreased insulin clearance, or both." (PMID 26225266, 2015). "Neither type of monotherapy affected plasma insulin levels, but the combination significantly ameliorated hyperinsulinemia." (PMID 25615826, 2015). "ZBH, but not bezafibrate, prevented mild hyperinsulinemia and reduced insulin insensitivity in the high fat-fed hamsters." (PMID 24759758, 2014). "Plasma insulin was elevated in HF diet-induced obese mice, but Rb1 did not significantly reverse hyperinsulinemia in these animals." (PMID 24675731, 2014). "We found that obese mothers, characterized by hyperinsulinemia and increased HOMA-IR-index, had decreased HMW adiponectin and SA which is in line with recent data from animal and clinical studies reporting that insulin is a negative regulator of adiponectin, preferentially HMW oligomer, secretion." (PMID 24720885, 2014). "Unfortunately, fasting blood samples were not collected from the mares before pregnancy so it is not possible to confirm hyperinsulinemia in non-pregnant pony mares, although excess BCS is associated with decreased insulin sensitivity in horses." (PMID 25006665, 2014). "Indeed, IDE deficient mice demonstrate increased cerebral accumulation of endogenous Aβ with hyperinsulinemia and glucose intolerance, and IDE overexpression ameliorates Aβ pathology, suggesting a link between insulin metabolism and Aβ degradation." (PMID 25368578, 2014). "Collectively, these findings indicate that RBP4 may play an important role in the mediation of signals related to proliferation of VSMCs induced by insulin, which suggests that RBP4 may contribute to vascular remodeling in hyperinsulinemia." (PMID 24604418, 2014). "Due to positive correlation of hyperinsulinemia and hypertriglyceridemia in third trimester with newborn weight at term, it is possible to assume that elevated TGs levels in GDM cases is a reflection of variation in maternal insulin levels." (PMID 24639763, 2013). "Thus, although insulin levels were elevated in fasted conditions in IRS-2(−/−) mice, expression of mRNAs coding for GK and GKRP was reduced, since in this model moderate hyperinsulinemia cannot compensate for the presence of severe hepatic insulin resistance." (PMID 23560040, 2013). "On the other hand, hyperinsulinemia is a human CRC promoter based on evidence that insulin is a colon epithelial cell mitogen in vitro, and insulin delivered via injection was shown recently to increase the incidence of azoxymethane-initiated colon tumors in rats." (PMID 24098689, 2013). "Chronic p110α inactivation might thus ameliorate the impact of age-related hyperinsulinemia and the lipotoxic effect of free fatty acids by promoting acute IRS-dependent insulin signalling." (PMID 23483710, 2013). "Using the C/I ratio as an index of hepatic insulin extraction rate or MCRI, the present data demonstrate that the basal C/I was significantly lower, which may also contribute to hyperinsulinemia in the DYS cynomolgus monkeys." (PMID 23886319, 2013). "The present data demonstrated that in addition to β-cell hypersecretion of insulin, reduced hepatic MCRI may also contribute to the development of hyperinsulinemia in the DYS monkeys." (PMID 23886319, 2013). "Since the affinity for the binding of insulin to IDE is much greater than the one for the Aβ peptide, hyperinsulinemia may lead to reduced Aβ peptide depurative mechanisms and accumulated concentration in the brain." (PMID 24386004, 2013). "However, hyperinsulinemia in young DU6 mice is normalized with advanced age, thus insulin in DU6 cannot explain the smooth control of glucose levels at higher ages." (PMID 24236159, 2013).
Hyperinsulinemia (continued). "Moreover, one study showed that insulin stimulated FGF21 expression during hyperinsulinemic clamp in obese T2DM patients, while the other study demonstrated that acute hyperinsulinemia tended to decrease FGF19 levels in healthy and T2DM subjects." (PMID 24260557, 2013). "In the current study we chose to use an in vivo model that was fully insulin responsive to address how hyperinsulinemia affects lipid dynamics in a system that is not insulin resistant or defective." (PMID 24069458, 2013). "Although the plasma insulin level was not determined in our study, the fact that the type 2 DM group had a higher BMI than the non-DM group was indirect evidence of relative hyperinsulinemia." (PMID 23383099, 2013). "In contrast, the hepatic insulin signaling in the Irs1−/− mice fed the HF diet was impaired, since Irs1 was absent and Irs2 signaling was suppressed by the hyperinsulinemia induced by the HF diet." (PMID 24284392, 2013). "Tesaglitazar greatly improved insulin's ability to suppress tissue nonoxidative FFA disposal resulting in normalization of Rfs at physiological hyperinsulinemia in all tissues examined." (PMID 24285952, 2013). "Insulin is an important neurotrophic factor, nevertheless, hyperinsulinism is not good news for diabetic patients." (PMID 24386004, 2013). "Likewise, fasting insulin level was significantly increased in the WT chimeras after HFD feeding, but hyperinsulinemia was less evident in the HFD-fed HO-1+/−chimeras." (PMID 22761690, 2012). "Furthermore, changes in circulating insulin levels were described to modulate cerebellar GLUT4 expression, and hyperinsulinemia led to regional changes in glucose utilization in rodent brain." (PMID 22500228, 2012). "Interestingly, hyperinsulinemia in NIRKO mice and insulin treatment in human NT2 neurons were described to decrease tau protein phosphorylation." (PMID 22500228, 2012). "Additionally, considering the fact that high C-peptide levels coexist with hyperinsulinemia, researchers would like to examine the role of C-peptide in prediction of the development of CVD in MetS as compared to insulin." (PMID 22899917, 2012). "On the other hand, adrenocortical biosynthesis, basally and in response to ACTH, are thought to be associated with glucose-mediated glucose disposal rather than the degree of hyperinsulinemia or insulin-mediated glucose disposal." (PMID 23216997, 2012). "Moreover, the findings in these studies are consistent with the pathophysiological process of hyperinsulinemia at the early stage of T2DM and the progressive impairment of insulin secretion over time." (PMID 23181120, 2012). "Hyperinsulinemia was also identified based on international cut-off points due to the lack of an upper limit of insulin values for Lebanese population." (PMID 22324838, 2012). "FATP2 mRNA remained at lower levels in the insulin-resistant group during fasting (p < 0.01) and the levels were not affected by hyperinsulinemia in either group." (PMID 22471940, 2012). "Thus, insulin stimulates endothelin-1 production and action through MAP-kinase-dependent pathways, while ET-1 induces IR and reactive hyperinsulinemia." (PMID 23046637, 2012). "In such a condition with hyperinsulinemia, where cells are not sensitive to insulin regulation, the extra insulin produced competes for the IDE and lowers the amount available for Aβ degradation." (PMID 22654727, 2011). "Burghen and colleagues observed a positive correlation between basal and glucose-stimulated insulin and androgen levels in PCOS, independent of weight, suggesting a causal relationship between hyperinsulinism and hyperandrogenism." (PMID 21899727, 2011). "Consistent with reports from clinical studies, treatment of DIO mice on the HF/CH diet with rosiglitazone increased the body weight and decreased hyperinsulinemia demonstrating the drug's insulin sensitizing effects (data not shown)." (PMID 20445733, 2010).
Hyperinsulinemia (continued). "In the 3T3-L1 preadipocyte differentiation assay, a validated model of insulin-sensitizing capacity, the 1 : 5 combination of RIAA and PAC increased lipid incorporation under the condition of hyperinsulinemia in a synergistic manner at all four concentrations tested." (PMID 20721358, 2010). "The extent to which hepatic fat accumulation and impaired insulin clearance contribute to hyperinsulinemia can not yet be regarded as fully understood." (PMID 20426802, 2010). "Abnormal fasting glucose values were not identified in any of the children, however IR occurred in 8.5% (23.1% in MS-children vs. 5.8% non-MS), hyperinsulinemia (plasma insulin >15 μUI/ml) in 7.3% and acanthosis was present in 22.0%." (PMID 20537155, 2010). "These opposite effects on IGFBP-1 production (insulin-independent stimulation versus insulin-dependent inhibition) observed in vitro, contrast with in vivo data showing that TZDs increase of IGFBP-1 synthesis, presumably because they reduce hyperinsulinemia." (PMID 19609453, 2009). "In our study, a marked increase in insulin concentration was found in SDD group that was attenuated after exercise training for 12 weeks, showing clearly the beneficial effects of physical exercise in management of hyperinsulinemia." (PMID 18510739, 2008). "Indeed, hyperinsulinemia is a regulator of senescence in most if not all human metabolic cells, and this is mediated by the pro-mitogenic effect of insulin, like that of IGF1." (PMID 41189469, 2026). "Glucose uptake measurements in differentiated myotubes can reflect insulin sensitivity and insulin resistance can be induced in cultured muscle cells from both non-diabetic and diabetic subjects through hyperinsulinemia, accompanied by increased GLUT1 but unaltered GLUT4 levels." (PMID 40346328, 2025). "Notably, co-incubation of insulin with the NOX inhibitor diphenyleneiodonium normalizes these changes, suggesting a functional link between oxidative stress and mitochondrial dysfunction under conditions of hyperinsulinemia." (PMID 40940776, 2025). "As a result, compensatory hyperinsulinemia not only fails to restore normal insulin signaling but may also accelerate atherosclerosis progression." (PMID 40370776, 2025). "However, given that hyperinsulinemia can exacerbate hyperandrogenism, particularly in PCOS, P. ovata’s potential to enhance insulin sensitivity could indirectly influence androgen levels." (PMID 40429855, 2025). "Our hypothesis that the RCD would reduce iatrogenic peripheral hyperinsulinemia, thereby enhancing insulin sensitivity and endothelial function, was not supported by the data." (PMID 40045281, 2025). "However, the role of IDE in hepatic insulin clearance is unclear, as liver-specific deletion of IDE does not cause hyperinsulinemia." (PMID 40522859, 2025). "Additionally, insulin is a negative regulator of both the transcription and flux of the rate-limiting ketogenic enzyme, HMGCS2, such that despite similar availability of FFAs, ketogenic potential is likely lower in the setting of (relative) hyperinsulinemia." (PMID 40662191, 2025). "Indeed, peripheral hyperinsulinemia leads to an increase in the insulin level in the brain, because the transport of molecules across the BBB is highly affected by the variation in their peripheral levels, especially the high level of insulin." (PMID 40943177, 2025). "The effect of morning hyperinsulinemia on PM glucose metabolism was profoundly diminished when morning insulin was administered via a peripheral route, yet there was a tendency for an enhancement in afternoon HGU that was proportional to the insulin levels at the liver." (PMID 39386695, 2024). "Therefore, SGLT2-I should be intensified alone or in combination with metformin to achieve insulin-independent antidiabetic pharmacotherapy that does not induce hyperinsulinemia." (PMID 38304078, 2024).
Hyperinsulinemia (continued). "Because insulin promotes activation of predominantly prohypertensive components of the RAS, hypertension in patients with IR may be largely related to hyperactivation of the RAS due to compensatory hyperinsulinemia accompanying IR." (PMID 38323106, 2024). "However, defining hyperinsulinemia consistently across studies remains challenging due to the absence of a widely accepted insulin concentration threshold." (PMID 38339407, 2024). "Therefore, hyperinsulinemia and the increase in bioavailable IGF-1 may be involved in tumor initiation and progression in insulin-resistant patients." (PMID 38392069, 2024). "The finding that catecholamines increased with each insulin dose is consistent with previous observations and may indicate that this response is an inherent, in vivo effect of hyperinsulinemia in humans and, thus, not an aberrant feature of our study." (PMID 38602778, 2024). "As hyperinsulinemia suppresses the production of SHBG, this could lead to a vicious circle leading to pronounced hyperinsulinemia via a compensatory increase in β-cell production of insulin." (PMID 39055720, 2024). "Concurrently, in the insulin-resistant state, this may be indicative of hyperinsulinemia or reflecting larger variabilities in plasma insulin, where the range of insulin secretion from islets required to maintain euglycemia is now much larger." (PMID 38568150, 2024). "Additionally, non-Hispanic Black and Hispanic individuals consistently showed higher prevalence rates of hyperinsulinemia and IR, as well as higher levels of fasting insulin and HOMA-IR index, compared to non-Hispanic White individuals." (PMID 39606490, 2024). "However, subcutaneous insulin delivery differs from endogenous insulin secretion which occurs directly into the hepatic portal system without producing peripheral hyperinsulinemia." (PMID 36845885, 2023). "Moreover, hyperinsulinemia suppresses hepatic production of VLDL1 but not VLDL2 in both insulin-sensitive and insulin-resistant humans with low liver fat." (PMID 37432744, 2023). "Strikingly, PK-ER;Ins2−/−;Ins1+/− mice (retaining a single copy of Ins1) exhibited reduced insulin levels and PanIN formation when fed a HFD compared with PK-ER;Ins2−/−;Ins1+/+ mice, arguing that HFD promotes pancreatic tumorigenesis via induction of hyperinsulinemia." (PMID 37648285, 2023). "Hyperinsulinemia may or may not maintain glucose homeostasis and is a state of insulin level that starts to drive pathological changes, first at the sub-cellular level and later at a macroscopic tissue and organ level." (PMID 37760052, 2023). "However, the exposure to sucrose-supplemented drinking water did result in hyperinsulinemia, elevated plasma PAI-1 levels and decreased insulin sensitivity, detected by two-way repeated-measures ANOVA (drinking water effect: p = 0.0004) and the calculated area under the curve." (PMID 36835405, 2023). "However, under conditions of hyperinsulinemia in T2DM and MS, this enzyme begins to hydrolyze insulin, which, competing with β-amyloid peptides, promotes the accumulation of β-amyloid aggregates in cerebral vessels, which is the reason for the close relationship between T2DM and AD." (PMID 36834685, 2023). "At the anterior pituitary level, peripheral hyperinsulinemia may contribute to the GnRH-stimulated LH hypersecretion and restoration of pituitary ESR1 expression is likely a mechanism by which insulin sensitizer treatment prevents LH hypersecretion in prenatal testosterone sheep." (PMID 36755919, 2023). "When we studied animals exposed during gestation to BPA during the first month of life, we found that on the first day of life they had greater β-cell area, and at day 30 mice had nonfasting hyperinsulinemia without alterations in glucose tolerance or insulin sensitivity." (PMID 37134142, 2023).